TRIB3 (tribbles pseudokinase 3)
Diseases named in the same sentence as TRIB3 in open-access papers (continued):
Sharing a sentence is not in itself a finding about the gene and the disease.
hepatocellular carcinoma (11 papers, 2020 to 2026). A malignant tumor that arises from hepatocytes. "Furthermore, stratifying the hepatocellular carcinoma cases of the TCGA cohort by their TRIB3 expression level revealed that a higher level of TRIB3 is associated with poorer survival." (PMID 34066165, 2021). "More interestingly, prolonged sorafenib exposure resulted in increased lung metastasis of hepatoma, an effect nullified upon TRIB3 knockout." (PMID 39932456, 2025). "First, a selective increase in Gr1+ neutrophils, but not other subsets of lymphocytes or myeloid cells, was detected in TRIB3‐overexpressing mouse hepatoma." (PMID 39932456, 2025). "Correspondingly, interruption of ROS‐ER stress axis significantly abrogated sorafenib‐induced TRIB3 upregulation and subsequent hepatoma growth and lung metastasis in vivo." (PMID 39932456, 2025). "Subsequently, we employed an anti‐Gr1 antibody to specifically deplete neutrophils in mice bearing wildtype or TRIB3‐overexpressing hepatoma." (PMID 39932456, 2025). "Consistent with this, a selective increase in Gr1+ neutrophils was detected in TRIB3‐overexpressing mouse hepatoma." (PMID 39932456, 2025). "Utilizing RNA sequencing, we identified 97 genes exhibiting upregulation in TRIB3‐overexpressing hepatoma tissue and annotated these genes using GO." (PMID 39932456, 2025). "Mechanistically, TRIB3‐amplified NF‐κB signaling upregulates CXCR1/2 ligands in hepatoma cells, attracting neutrophils that enhance EMT via the OSM‐STAT3 pathway, thereby diminishing sorafenib's efficacy." (PMID 39932456, 2025). "To assess the expression levels of TRIB3 in liver tumors in vivo, we ranked the tumor types from TCGA by median expression of TRIB3, which revealed that hepatocellular carcinoma has the highest median TRIB3 level out of all TCGA tumor types." (PMID 34066165, 2021). "The survival of bortezomib-exposed hepatoma cells proved sensitive to TRIB3 overexpression and inactivation." (PMID 34066165, 2021). "Taken together, the results indicate that TRIB3, a gene highly expressed in hepatic cancers, functions as a factor promoting resistance to bortezomib in hepatoma cells." (PMID 34066165, 2021). "To test whether induction of TRIB3 by sorafenib is dependent on in vivo cancer environments, we directly subjected hepatoma cell lines—Huh‐7, MHCC‐97H, Hep G2, and SNU‐449—to sorafenib in vitro." (PMID 39932456, 2025). "We subsequently examined the impact of TRIB3 on cancer hallmarks in hepatoma‐bearing mice." (PMID 39932456, 2025). "Similarly, in sorafenib‐treated hepatoma cells, overexpression of TRIB3 amplified NF‐κB signaling activation, while its knockout attenuated this effect." (PMID 39932456, 2025). "Consistent with our hypothesis, neutrophil depletion effectively attenuated the aggressive angiogenesis and the enhanced EMT process in hepatoma driven by TRIB3 overexpression." (PMID 39932456, 2025). "Furthermore, in support of the findings demonstrating TRIB3's promotion of hepatoma growth and lung metastasis, treatment with a PERK inhibitor or NAC also inhibited hepatoma growth and lung metastasis in mice." (PMID 39932456, 2025). "Indeed, during sorafenib treatment, both TRIB3 expression and neutrophil infiltration were progressively upregulated in the Hepa1‐6 hepatoma." (PMID 39932456, 2025). "Also, compared to their wildtype counterparts, hepatoma cells overexpressing TRIB3 exhibited significantly elevated levels of CXCR1/2 ligands." (PMID 39932456, 2025). "In fact, whether in mouse hepatoma models (either orthotopic or spontaneous), or in vivo culture of hepatoma cells, sorafenib administration markedly elevated TRIB3 expression." (PMID 39932456, 2025). "For example, Sp2 knockdown in hepatocellular carcinoma cells decreases cell migration, proliferation and survival of hepatocellular carcinoma cells and this is due, in part, to decreasing the expression of the TRIB3 gene." (PMID 36982239, 2023).
hepatocellular carcinoma (continued). "SP2 targets TRIB3 to facilitate the migration and invasion ability of hepatocellular carcinoma." (PMID 34307888, 2021). "Since pharmacological perturbation of ATF4 activity affected cell sensitivity to bortezomib, these results raise the possibility that hepatoma cells employ high TRIB3 expression to achieve optimal ATF4 pathway activity and thereby survival under stressful conditions." (PMID 34066165, 2021). "A coincident TRIB3-dependent phenotype was observed for human hepatoma HepG2 cells." (PMID 34198908, 2021). "Here, we identify the pseudokinase TRIB3 as a key mediator of the metabolic adaptation of hepatocellular carcinoma (HCC) cells to limiting glutamine availability." (PMID 41793192, 2026). "Similarly, TRIB3 knockout minimally impacted the EMT process in hepatoma cells." (PMID 39932456, 2025). "This study uncovered a novel mechanism underlying the developed resistance to sorafenib in hepatocellular carcinoma (HCC), highlighting the pivotal role of TRIB3 in this process." (PMID 39932456, 2025). "Thus, elevated TRIB3 may promote hepatoma progression through a pathway dependent on neutrophil activity." (PMID 39932456, 2025). "Among hepatoma cell lines, cell viability data from both drug screening projects revealed a positive correlation between resistance to bortezomib and the expression level of TRIB3, a gene upregulated by bortezomib and known to be a negative regulator of the ATF4 pathway." (PMID 34066165, 2021). "Hence, multiple ATF4 target genes are co-bound by TRIB3 and might participate in the regulation of cell death in response to bortezomib treatment in hepatocellular carcinoma cells." (PMID 34066165, 2021). "Accordingly, inhibition of NF‐κB signaling activity through p65 knockdown effectively countered TRIB3‐mediated neutrophil infiltration, thereby mitigating subsequent enhancements in angiogenesis and EMT within hepatoma tissue." (PMID 39932456, 2025). "Third, neutrophil depletion effectively attenuated TRIB3‐driven aggressive angiogenesis and the enhanced EMT process in hepatoma, and thereby augment the anti‐tumor efficacy of sorafenib treatment." (PMID 39932456, 2025). "To ascertain whether the upregulation of TRIB3 induced by sorafenib contributes to therapeutic resistance, we established sorafenib therapeutic strategy in mice bearing orthotropic Hepa1‐6 cell‐derived hepatoma or hydrodynamic force‐induced spontaneous hepatoma." (PMID 39932456, 2025). "The ability of the protein TRIB3 to bind a large portion of genomic sites occupied by ATF4 and restrict ATF4-dependent transcription promotes hepatoma cells resistance to bortezomib treatment." (PMID 34066165, 2021). "In the present article, we characterize the effect of pharmacological modulators of the eIF2α–ATF4 pathway, and of TRIB3, an endogenous inhibitor of ATF4, on the gene expression and viability of HepG2 human hepatoma cells exposed to bortezomib." (PMID 34066165, 2021). "The pseudokinase TRIB3, an inhibitor of ATF4, is expressed at a high basal level in hepatoma cells and is strongly upregulated in response to bortezomib." (PMID 34066165, 2021). "The experiment discovered that the expression of TRIB3 and GRP78 in Sp2 silenced hepatoma cells decreased significantly." (PMID 32160655, 2020). "In contrast to in vitro observations, in vivo overexpression of TRIB3 significantly enhanced hepatoma cell proliferation and EMT, as evidenced by increased Ki67 expression in hepatoma cells and alterations in vimentin and E‐cadherin levels under long‐term sorafenib treatment." (PMID 39932456, 2025). "Accordingly, in the neutrophil‐depleted mouse model, TRIB3 overexpression failed to promote hepatoma growth and lung metastasis." (PMID 39932456, 2025). "Subsequently, given the successful suppression of sorafenib‐induced lung metastasis in vivo upon TRIB3 knockout, we explored whether TRIB3 signaling initiated epithelial‐mesenchymal transition (EMT) in hepatoma cells." (PMID 39932456, 2025).
hepatocellular carcinoma (continued). "Consistent with this, sorafenib treatment led to increased infiltration of Gr1+ neutrophils in hepatoma tissues, an effect that was absent in TRIB3 knockout hepatoma cells or was suppressed by administration of the CXCR1/2 inhibitor Reparixin." (PMID 39932456, 2025). "Notably, also in such a model, knockout of TRIB3 accentuated sorafenib's therapeutic effect, fostering sustained hepatoma regression, although this treatment marginally affected hepatoma growth in the absence of sorafenib." (PMID 39932456, 2025). "Moreover, notably in the neutrophil‐depleted mouse model, sorafenib treatment resulted in sustained hepatoma regression and did not exacerbate the metastatic potential of hepatoma, and this effect was comparable to that observed in TRIB3 knockout mice." (PMID 39932456, 2025). "Intriguingly, its relationship with exosomes has also been investigated, indicating that TRIB3 could mediate the impairment of autophagy and facilitate the secretion of INHBA/Activin A-enriched exosomes of hepatocellular carcinoma, thus resulting in the occurrence of liver fibrosis." (PMID 37153569, 2023).
type 2 diabetes (11 papers, 2013 to 2025). "The Drosophila pseudokinase Tribbles (Trbl) shares conserved functions with human TRIB3 to bind and inhibit Akt phosphorylation-activation by the Insulin Receptor (InR) to reduce insulin responses; consistent with this, increased levels of human TRIB3 are linked to type 2 diabetes." (PMID 40292740, 2025). "Moreover, a Trbl mutant designed to mimic a Trib3 variant associated with type 2 diabetes in humans contributed to insulin-resistant phenotypes in the larval model." (PMID 33672471, 2021). "Interestingly, the predominant Q84 glutamine variant is unique to the genus Homo, as the rare R variant associated with predisposition to human Type 2 diabetes is found at this position in Trib3 in other vertebrates and in Trib1 and Trib2 in all vertebrates." (PMID 29025897, 2017). "The TRIB3 33bp VNTR polymorphisms were determined by PCR and Sanger sequencing, a total of 798 eligible Chinese patients with type 2 diabetes (T2DM) were included in our study and then evaluated with clinical data." (PMID 36105108, 2022). "Previous studies in type 2 diabetic rats showed that silencing the TRIB3 gene effectively reversed aortic remodeling and improved vascular compliance." (PMID 36105108, 2022). "And TRIB3 (rs2295490) AG/GG genotypes were found to reduce primary vascular events in type 2 diabetic patients who received intensive glucose treatment as compared to those receiving standard glucose treatment." (PMID 30971918, 2019). "While several variants have been described over the years for all these genes, solid evidence of an association with type 2 diabetes and related diseases seems to exist only for rs1044498 of the ENPP1 gene and for rs2295490 of the TRIB3 gene." (PMID 23762820, 2013). "Additionally, in a rat model of type 2 diabetes, TRIB3 gene silencing reverted myocardial remodeling by restoring Akt activation and reducing the increased activation of MAPK." (PMID 34051802, 2021). "TRIB3 (rs2295490) AG/GG genotypes were found to reduce primary vascular events in patients who received intensive glucose treatment as compared to those receiving standard glucose treatment in type 2 diabetic patients." (PMID 30971918, 2019). "In obese patients with or without type 2 diabetes, the expression of TRIB3 was higher than that in the control group." (PMID 36105108, 2022).
acute promyelocytic leukemia (10 papers, 2018 to 2024). An aggressive form of acute myeloid leukemia (AML), characterized by arrest of leukocyte differentiation at the promyelocyte stage, due to a specific chromosomal translocation t(15;17) in myeloid cells. "Our result was consistent with the previous reports that TRIB3 was significantly correlated with the degree of bone marrow differentiation in patients with acute promyelocytic leukemia." (PMID 34957220, 2021). "Furthermore, it has been indicated that TRIB3 has a pro-tumorigenic function in renal clear cell carcinoma, liver cancer, lung adenocarcinoma, and acute promyelocytic leukemia." (PMID 38235126, 2023). "However, evidence suggests that TRIB3 contributes to acute promyelocytic leukemia progression by PML‐RARα stabilization via specific binding to SUMOylation motifs, thereby acting on PML‐RARα degradation and differentiation." (PMID 31254352, 2019). "It disrupts the TRIB3-SQSTM1 or TRIB3-PML/RAR α interaction through specific peptides, and this is a potential strategy for treating certain solid cancers and acute promyelocytic leukemia." (PMID 33841505, 2021). "Consistently, TWIST1 levels were also observed to be high in acute promyelocytic leukemia (APL) cells, a sub-population of AML, and this event was shown to be due to its interaction with tribbles pseudokinase 3 (TRIB3), protecting it from degradation processes." (PMID 38396852, 2024). "Studies reported that knocking out TRIB3 inhibited tumor formation and cancer progression, disrupting TRIB3–SQSTM1 or TRIB3–PML/RARα interactions through specific peptides, which is a potential strategy for treatment of certain solid cancers and acute promyelocytic leukemia." (PMID 32874132, 2020).
endometrial cancer (10 papers, 2020 to 2025). Primary or metastatic malignant neoplasm involving the endometrium (mucous membrane that lines the endometrial cavity). "And it’s found that TRIB3 expression change is part of the anti-endometrial cancer activities in one ongoing clinical trial." (PMID 37880674, 2023). "In endometrial cancer cells, TRIB3 enhanced cell apoptosis and suppressed cell proliferation and migration ability through inhibition of Akt." (PMID 34503515, 2021). "Qu et al27 point out that TRIB3 has a higher expression in human endometrial cancer than in benign endometrial tissue and normal tissues." (PMID 32160655, 2020). "Only few studies have reported the role of TRIB3 expression in gynecological tumors, and these are limited to endometrial cancer." (PMID 32874132, 2020). "Still, biological experiments showed TRIB3 has a tumor suppressing effect in endometrial cancer, which can promote tumor cell apoptosis and reduce tumor cell proliferation and migration." (PMID 32160655, 2020). "In endometrial cancer, ELF4, acting as a transcriptional activator, is recruited to the promoter of catenin beta 1 (CTNNB1; encoding β-catenin) by tribbles pseudokinase 3 (TRIB3), thereby enhancing oncogenesis and self-renewal of cancer stem cells." (PMID 40083328, 2025). "In endometrial cancer, ELF4 acts as the effector of TRIB3 to drive tumorigenesis." (PMID 36923538, 2023). "Unlike what it has been described for lung, pancreatic and endometrial cancer cells, ABTL0812 does not reduce phosphorylation of AKT or mTORC1 substrates, despite inducing the upregulation of TRIB3 and LC3-II levels." (PMID 32943619, 2020).
gastric cancer (10 papers, 2019 to 2026). A primary or metastatic malignant neoplasm involving the stomach. "Dong et al23 reported that TRIB3 is overexpressing in human gastric cancer, which was associated with the tumor angiogenesis and poor prognosis." (PMID 32160655, 2020). "Overexpression of TRIB3 is associated with tumor angiogenesis and a poor prognosis in patients with gastric cancer, and patients with high TRIB3 expression were susceptible to a recurrence of the disease, and showed poorer overall survival than those with low expression." (PMID 30763339, 2019). "In summary, PTPRE suppresses ferroptosis in gastric cancer cells via the Src/FAK/TRIB3 signalling pathway, thereby inducing 5-FU resistance." (PMID 42313735, 2026). "TRIB3 overexpression in human gastric cancer was related to tumor angiogenesis and a poor prognosis." (PMID 37626099, 2023). "TRIB3 has also been shown to plays an anti-apoptotic role in doxorubicin-treated gastric cancer cell lines and be highly expressed in gastric cancer tumors, and is related to poor patient prognosis." (PMID 35726370, 2022). "TRIB3 silencing suppresses VEGF−A expression in gastric cancer cells inhibiting endothelial cell migration and vessel formation." (PMID 34249670, 2021). "In diagnostics, while FABP1 combined with TRIB3 can improve the sensitivity of early gastric cancer diagnosis, and FABP6 combined with CEA can enhance CRC diagnostic efficacy, the specificity of single biomarkers and expression heterogeneity across different cancer types limit clinical application." (PMID 40717587, 2025). "Mechanistic studies revealed that PTPRE suppressed ferroptosis in gastric cancer cells and promoted 5-FU resistance by activating the Src/FAK pathway to upregulate TRIB3 expression." (PMID 42313735, 2026). "Specifically focusing on gastric cancer cases (STAD) within the TCGA, we found a very low frequency of TRIBs genetic and genomic alterations (TRIB1: 9.4%, TRIB2: 2.1%, and TRIB3: 2.1%)." (PMID 38254916, 2023).
Hyperglycemia (10 papers, 2010 to 2025). An increased concentration of glucose in the blood. "To support in vivo evidence for the functional role of FTO and TRIB3 in wound closure under consistent hyperglycemia, we established diabetic wound models with C57BL/6 mice." (PMID 40157922, 2025). "Each of these pathways contributes to the upregulation of TRIB3, which in turn plays a pivotal role in managing the cellular responses to hyperglycemia, particularly in the context of DN." (PMID 38733632, 2024). "TRIB3 is a protein closely related to metabolism, and can be induced by a series of metabolism factors prevalent in DM, such as hyperglycemia, hyperinsulinemia, and IGF-1." (PMID 29367413, 2018). "Interestingly, TRIB3, a metabolic stress indicator, is elevated in response to hyperglycemia as documented in another study by our group on diabetic humans and mice." (PMID 35046899, 2021). "The first putative mechanism may involve Trib3, which is known to be induced in a broad range of cells and in response to multiple forms of cellular stress such as ER stress, excess of free fatty acids, oxidative stress, hypoxia, hyperglycemia, and toxins." (PMID 33210603, 2020).